GAPDH (glyceraldehyde-3-phosphate dehydrogenase)
Diseases named in the same sentence as GAPDH in open-access papers (continued):
Sharing a sentence is not in itself a finding about the gene and the disease.
bowel cancer (2 papers, 2022 to 2025). "The genes with the highest posterior probability of being associated with bowel cancer alone were APC (0.48) and GAPDH (0.48)." (PMID 40073867, 2025). "Thus, cancer cells with high level of RAS mutation are highly vulnerable to glycolytic inhibitors, as evidenced by the downregulation of glycolytic enzyme glyceraldehyde 3-phosphate dehydrogenase (GAPDH) and impaired tumor growth in vitamin C treated KRAS mutant mouse intestinal cancers." (PMID 36510194, 2022).
brain ischemia (2 papers, 2012 to 2014). Diminished or absent blood supply to the brain caused by obstruction (thrombosis or embolism) of an artery resulting in neurologic damage. "Disruption of GluR2/GAPDH interaction by administration of an interfering peptide prevents AMPAR-mediated excitotoxicity and protects against damage induced by oxygen-glucose deprivation (OGD), an in vitro model of brain ischemia." (PMID 22537872, 2012).
Burkitt lymphoma (2 papers, 2016 to 2025). A rare form of malignant mature B-cell non-Hodgkin lymphoma. "The same three cell lines—Namalwa and RAJI (EBV-positive Burkitt lymphoma) and SUDHL-4 (EBV-negative diffuse large B-cell lymphoma)—were assessed using gp350-specific antibodies, with GAPDH serving as a loading control." (PMID 39930509, 2025).
cardiac hypertrophy (2 papers, 2023 to 2024). "We demonstrated that co‐treatment with SE and harmine significantly decreased key metabolic markers, including LA, PA, G6P, the NAD+/NADH ratio, the activity of GAPDH, and ATP production in AngII‐induced cardiac hypertrophy models." (PMID 39351650, 2024). "GAPDH is known as glyceraldehyde-3-phosphate dehydrogenase (GAPDH), which is the most important enzyme in cardiovascular hypertrophy." (PMID 38007574, 2023).
cataract (2 papers, 2023 to 2024). Partial or complete opacity of the crystalline lens of one or both eyes that decreases visual acuity and eventually results in blindness. "The addition of vitamin E to the incubation medium inhibited further progression of cataracts, reduced increases in lipid peroxide levels and the Na+/K+ ratio, and ameliorated decreases in reduced glutathione, glyceraldehyde-3-phosphate dehydrogenase, and Na+/K+-ATPase activities." (PMID 39183990, 2024). "In the lens of people with PD and cataract, glyceraldehyde-3-phosphate dehydrogenase function, which is implicated in glycolysis and apoptosis activation, is decreased compared to patients who have cataracts without having PD." (PMID 36810467, 2023).
cholangiocarcinoma (2 papers, 2020 to 2022). A carcinoma that arises from the intrahepatic biliary tree (intrahepatic cholangiocarcinoma) or from the junction, or adjacent to the junction, of the right and left hepatic ducts (hilar cholangiocarcinoma). "Since there is currently no consensus on the most suitable housekeeping proteins in cholangiocarcinoma, we chose to use GAPDH and TUBB as housekeeping proteins since they are commonly used for this purpose and because suitable peptides were available in the discovery study data." (PMID 32887625, 2020).
chondrosarcoma (2 papers, 2021 to 2022). A malignant cartilaginous matrix-producing mesenchymal neoplasm arising from the bone and soft tissue. "Since it has been reported that GAPDH is secreted through an unconventional mechanism and is also strongly associated with EVs, we further investigated its extracellular compartmentalization to confirm that GAPDH could also be secreted by this dual mechanism in chondrosarcoma cells." (PMID 35893766, 2022). "Among these proteins, which may be used to monitor chondrosarcoma development, we validated the increased secretion in response to hypoxia of glyceraldehyde 3-phosphate dehydrogenase (GAPDH), a glycolytic enzyme well-known for its different functional roles in a wide range of tumors." (PMID 35893766, 2022). "In addition to molecular processes that are altered in response to hypoxia and which provide new information about chondrosarcoma progression, we identified a number of proteins, including GAPDH, that may be further developed as predictive and/or prognostic biomarkers for chondrosarcoma." (PMID 35893766, 2022). "GAPDH and other proteins whose secretion was augmented in response to hypoxia, including CNBP and SNRPA, could represent proteomic signatures of chondrosarcoma and could be developed as chondrosarcoma biomarkers." (PMID 35893766, 2022). "In addition, we identified a number of proteins whose secretion was increased in response to hypoxia, including glyceraldehyde 3-phosphate dehydrogenase (GAPDH), which may be further developed as prognostic biomarkers of chondrosarcoma." (PMID 35893766, 2022).
chronic pancreatitis (2 papers, 2016 to 2023). A chronic inflammatory process causing damage and fibrosis of the pancreatic parenchyma. "ALDH3B1, ENO1, ALDH2, GAPDH, and LDHC had significant differences among grades, while ALDH3B1, PKM, and ALDH3B2 differed among chronic pancreatitis histories." (PMID 36814901, 2023).
colorectal adenocarcinoma (2 papers, 2010 to 2022). The most common type of colorectal carcinoma. "mRNA expression of DDC in colorectal adenocarcinoma tissues varied from 0.04 to 91.95 c/Kc (DDC mRNA copies per 1000 GAPDH mRNA copies) with a mean±s.e." (PMID 20424616, 2010).
congenital muscular dystrophy (2 papers, 2013 to 2021). A muscular dystrophy that is characterized by diminished muscle tone (hypotonia), progressive muscle weakness and degeneration (atrophy), abnormally fixed joints, spinal rigidity, and delays in reaching motor milestones such as sitting or standing unassisted. "GAPDH has been targeted with the investigational drug Omigapil for prevention of PD, ALS, congenital muscular dystrophy and myopathy." (PMID 34745218, 2021).
cyst (2 papers, 2018 to 2019). A sac-like closed membranous structure that may be empty or contain fluid or amorphous material. "In support of this idea, the lectins had the same localization in mature cyst walls when expressed as an internal probe with a GFP-tag under its own or under a constitutive GAPDH promoter or when applied externally as an MBP-fusion." (PMID 31095564, 2019). "Despite a large difference in 18S Ct values when compared to viruses, it was necessary to use 18S as a control across cyst nematode species as GAPDH and HgFAR1 primers did not work well outside of SCN." (PMID 29509804, 2018).
cystic kidney disease (2 papers, 2018 to 2020). A congenital or acquired kidney disorder characterized by the presence of renal cysts. "In contrast, in mouse models of renal cystic disease, GAPDH, peptidylprolyl isomerase A and phosphoglycerate kinase have been ranked highest, highlighting the need for model, species and strain specific housekeeping genes." (PMID 32437461, 2020). "GAPDH, PPIA and PGK1 were also recommended as reference transcripts in studies about mice with cystic kidney disease." (PMID 29534701, 2018).
ependymoma (2 papers, 2014 to 2021). A WHO grade II, slow growing tumor of children and young adults, usually located intraventricularly. "In comparison to the housekeeping gene GAPDH, varying levels of BLBP were recorded in all ependymoma cell lines." (PMID 33925302, 2021).
esophageal squamous cell carcinoma (2 papers, 2017 to 2022). Esophageal squamous cell carcinoma (ESCC) is a type of esophageal carcinoma (EC) that can affect any part of the esophagus, but is usually located in the upper or middle third. "For the two commonly used reference genes, ATCB and GAPDH, the ranking was the median in the results of this experiment, indicating that the expression in esophageal squamous cell carcinoma was not stable enough." (PMID 36467891, 2022).
experimental autoimmune encephalomyelitis (2 papers, 2019 to 2022). An autoimmune demyelinating disease of the central nervous system that is produced experimentally in animals by the injection of homogenized brain or spinal cord in Freund's adjuvant. "Here, we demonstrate that the multifunctional protein glyceraldehyde-3-phosphate dehydrogenase (GAPDH) is robustly nitrosylated in the CNS in the experimental autoimmune encephalomyelitis (EAE) mouse model of MS." (PMID 36761918, 2022). "Dimethyl fumarate, a derivative of the Krebs cycle intermediate fumarate that inactivates glyceraldehyde 3-phosphate dehydrogenase (GAPDH), attenuated Th1 and Th17 responses in the experimental autoimmune encephalomyelitis model." (PMID 31057554, 2019).
fibrosis (2 papers, 2017 to 2020). the formation of excess fibrous connective tissue in an organ or tissue in a reparative or reactive process. "In addition, GAPDH expression was also increased in our cocultured PF, and although it is frequently employed as a housekeeping gene, GAPDH overexpression in fibroblasts has been shown to correlate with fibrosis and with an altered metabolism adapted to support a rapid cell growth." (PMID 32133790, 2020).
fungal infection (2 papers, 2016 to 2024). "Such a mechanism may indicate how soluble GAPDH can be deposited onto the fungal cell surface at sites of fungal infection." (PMID 38256088, 2024). "The best reference genes for use as normalizers in our study were EF, EIF4A and GAPDH for the different developmental stages and body parts; EF, RPL13A and EIF4A for the low-temperature challenge; and EF, EIF4A and TUB for both the fungal infection and dietary treatments." (PMID 27392023, 2016). "The 3 most stable genes were EIF4A, GAPDH and TUB for the different developmental stages; EIF4A, GAPDH and EF for the different body parts; EF, RPL13A and GAPDH for the low-temperature challenge; G6PDH, 18S and EIF4A for fungal infection; and EF, GAPDH and TUB for the different diets treatment." (PMID 27392023, 2016).
goiter (2 papers, 2014 to 2020). Enlargement of the thyroid gland usually caused by lack of iodine in the diet, hyperthyroidism, or thyroid nodules. "The genes with the lowest variations in expression for normal samples, goiter, and all samples were, respectively, GAPDH, ACTB, SDHA and ACTB, when evaluated by the NormFinder." (PMID 24900955, 2014). "The most stable genes were ACTB for goiter and GAPDH for normal thyroid tissue." (PMID 24900955, 2014). "Considering these criteria, none of the selected genes could be used to normalize RT-qPCR data for goiter tissues, and GAPDH and SDHA could be used for normal thyroid." (PMID 24900955, 2014). "In conclusion, the results of the present study suggest that ACTB gene is more stable than SDHA, GAPDH, HPRTI, YWHAZ, and B2M when evaluating human normal thyroid and goiter together." (PMID 24900955, 2014).
Hepatitis (2 papers, 2013 to 2014). Inflammation of the liver. "GAPDH has been shown to physically interact with RNA from Japanese encephalitis, hepatitis A and parainfluenza viruses." (PMID 24667214, 2014).
Hyperinsulinemia (2 papers, 2013 to 2017). An increased concentration of insulin in the blood. "In addition, hyperinsulinemia downregulates GAPDH, one of the key glycolysis enzymes, which can then activate the pentose phosphorylation pathway with a concomitant increase of purine synthesis de novo." (PMID 24454499, 2013). "Long-term hyperinsulinemia can interfere with carbohydrate metabolism and weaken GA3PDH (glyceraldehyde-3-phosphate dehydrogenase) activity, which promotes the glycolytic metabolism of intermediate synthesis of ribose-5-phosphate (R-5-P), phosphoric acid (PPRP), and uric acid." (PMID 29109738, 2017).
Hypoglycemia (2 papers, 2016 to 2025). A decreased concentration of glucose in the blood. "Similar results were obtained with the HeLa model under hypoglycemia when modulation of the GAPDH, PYK, PGK, PGAM, and LDH activities were simulated." (PMID 27721794, 2016). "Interestingly, BA-induced GAPDH upregulation in T24 cancer cells may offer a potential alternative mechanism for raising FDG uptake into tumors without triggering the hypoglycemia risk." (PMID 40565062, 2025).
idiopathic scoliosis (2 papers, 2013 to 2019). A scoliosis with no known cause. "Specially designed artificial neural network model proved possible association between expression level of ACTB, GAPDH and positive familial history of Idiopathic Scoliosis." (PMID 23289769, 2013). "In addition, possible association between expression level of ACTB, GAPDH and familial history of idiopathic scoliosis was proved." (PMID 31653238, 2019). "The analysis indicates the relationship between level of expression of ACTB, GAPDH and familial Idiopathic Scoliosis." (PMID 23289769, 2013). "The aim of the study was to investigate whether the expression levels of ACTB and GAPDH in different tissues of idiopathic scoliosis patients could be used as source of data for specially developed artificial neural network in order to predict the positive family history of index patients." (PMID 23289769, 2013). "The aim of the study was to investigate whether the expression levels of ACTB and GAPDH in different tissues of idiopathic scoliosis patients could be used as a source of data for specially developed artificial neural network in order to predict the positive family history of index patient." (PMID 23289769, 2013). "The classification accuracy for Idiopathic Scoliosis in the anamnesis with expression measurement of ACTB and GAPDH with use of ANN based on 6-18-16-1 architecture was 8 of 9 (88%)." (PMID 23289769, 2013). "The classification accuracy for positive Idiopathic Scoliosis anamnesis only with the expression measurements of ACTB and GAPDH with the use of ANN based on 6-18-16-1 architecture was 8 of 9 (88%)." (PMID 23289769, 2013). "An artificial neural network (ANN) was developed that could serve to differentiate between familial and sporadic cases of idiopathic scoliosis based on the expression levels of ACTB and GAPDH in different tissues of scoliotic patients." (PMID 23289769, 2013).
leprosy (2 papers, 2014 to 2018). Leprosy is a chronic infectious disease affecting primarily the skin and peripheral nervous system. "We further observed a significantly lower VDR/GAPDH mRNA expression ratio in TT/BT and BL/LL groups of leprosy in comparison to HC group." (PMID 30481178, 2018). "Highest VDR/GAPDH gene expression ratio was observed in T2R cases in comparison to all the phenotypes of leprosy." (PMID 30481178, 2018). "The mean mRNA expression ratios of VDR/GAPDH are identified to be significantly lower in TT/BT and BL/LL group of leprosy in comparison to the HC (TT/BT vs. HC, 0.702 vs. 1.076 and BL/LL vs HC, 0.462 vs 1.076 p < 0.05)." (PMID 30481178, 2018). "Cytokine expression normalized by GAPDH in dermal leprosy lesions." (PMID 25412496, 2014). "Highest mean mRNA expression ratio of VDR/GAPDH was observed in T2R group of leprosy however it is not significant in comparison to HC (T2R vs HC 5.62 vs 1.076, p>0.05) followed by T1R (1.044)." (PMID 30481178, 2018). "Further, when we compared mean mRNA expression ratio of VDR/GAPDH between non-reaction (NR) and T1R/T2R groups of leprosy, it was noted that the ratio is not significantly different between the groups (NR vs T1R 0.5894 vs 1.044, p = 0.05; NR vs T2R 0.5894 vs 5.62, p = 0.9529)." (PMID 30481178, 2018).
mammary adenocarcinoma (2 papers, 2019).
meningitis (2 papers, 2014 to 2021). A disorder characterized by acute inflammation of the meninges of the brain and/or spinal cord. "The CP isolated from piglets suffering from meningitis showed a clear inflammatory response by the increased expression (enhanced signal when referencing the GAPDH signal) of the genes encoding IL1β and IL8, as compared to the meningitis-free piglets." (PMID 33763387, 2021).
mesothelioma (2 papers, 2008 to 2023). A usually malignant and aggressive neoplasm of the mesothelium which is often associated with exposure to asbestos. "The relative expression of the archetypal, full-length, transmembrane MUC1 isoform, MUC1-TM, normalised to GAPDH, was significantly greater in the cells from pleural effusion (P<0.0001) and surgically-excised tumour (P=0.001) mesothelioma samples than that in normal mesothelial cells." (PMID 18454162, 2008).
metastatic disease (2 papers, 2023). "We identified a new cluster of IL32 + B cells (BC2) that are CD38-SDC1-S100A4+GAPDH+; these cells were found in both primary and metastatic tumor sites with high T cell infiltration, deriving primarily in clear cells and SOC histotypes." (PMID 38328306, 2023).
myopia (2 papers, 2009 to 2023). "In a mouse model of myopia induced by the wearing of a negative lens on one eye, we observed high levels of TGM-2 protein staining in the sclera and elevated TGM-2 transcription levels and protein levels in myopic sclera compared to the control sclera (normalized to the GAPDH)." (PMID 37509081, 2023).
ovarian serous cancers (2 papers, 2004 to 2013). "High GAPDH or low BEC-index mRNA expression indicate early disease progression in advanced serous ovarian cancer." (PMID 24252137, 2013). "We have earlier shown HSP60 overexpression to predict poor outcome in serous ovarian cancer, and the BEC-index data from the present study probably reflects both the tumor material’s GAPDH and HSP60 expression." (PMID 24252137, 2013). "In order to validate the gene-expression levels from the microarray experiments, we performed real-time qRT–PCR with GAPDH as a control in five normal ovaries, three LMP ovarian serous cancers, five primary ovarian serous cystadenocarcinomas and two omental metastases." (PMID 14760385, 2004).
ovarian tumor (2 papers, 2016 to 2022). "Expression levels of CD13 and integrin αvβ3 in three ovarian tumor cell lines were determined via Western blot, with GAPDH used as an internal control." (PMID 35664759, 2022).
papilloma (2 papers, 2011 to 2020). A benign epithelial neoplasm that projects above the surrounding epithelial surface and consists of villous or arborescent outgrowths of fibrovascular stroma. "ROPV copy number was very high at sites bearing visible papillomas, with 104 to 105 copies of ROPV DNA per copy of GAPDH." (PMID 21492895, 2011). "Moving from the basal layers toward the surface of the papilloma, there was a gradual increase in ROPV DNA copy number relative to the glyceraldehyde-3-phosphate dehydrogenase (GAPDH) reference gene, indicative of amplification of viral DNA." (PMID 21492895, 2011). "Immature LCs from the papillomas and foreskin expressed high levels of CCL20 mRNA that were close to GAPDH levels at baseline, with no significant change after removal from their microenvironments or following stimulation with either poly(I:C) or TNFα." (PMID 32210959, 2020). "However, for these rabbits (which no longer bear visible papillomas), ROPV DNA copy numbers were between six and nine log-fold lower at 10− 5 to 10− 2 copies of ROPV DNA per copy of GAPDH compared to productive infection." (PMID 21492895, 2011).
peritonitis (2 papers, 2015 to 2016). Inflammation of the peritoneum (tissue that lines the abdominal wall and covers most of the organs in the abdomen). "Indeed, relative expression level of Arg1 to a control house keeper gene (GAPDH) in these peritoneal-elucidated cells at healing stage of peritonitis was as high as that in in vitro-activated M2MΦs by recombinant IL-4." (PMID 27731330, 2016). "As in case of TG induced peritonitis, here too we found enhanced levels of GAPDH in serum and enhanced sequestration of iron in peritoneal cells isolated from E.coli infected mice, a strategy used to deny the availability of this vital element to the invading pathogen." (PMID 26672975, 2015). "In mice with thioglycolate induced acute peritonitis we observed enhanced serum GAPDH, suggesting that this may contribute to enhance the Lf sequestering capabilities of host cells." (PMID 26672975, 2015).